GAK (cyclin G associated kinase)
Description:
Associates with cyclin G and CDK5. Seems to act as an auxilin homolog that is involved in the uncoating of clathrin-coated vesicles by Hsc70 in non-neuronal cells. Expression oscillates slightly during the cell cycle, peaking at G1. May play a role in clathrin-mediated endocytosis and intracellular trafficking, and in the dynamics of clathrin assembly/disassembly.
Synonyms: DNAJC26; DNAJ26
Tractability: Small molecule: a structure with a bound ligand is known; a high-quality ligand is known; it has a high-quality binding pocket; it belongs to a druggable protein family. PROTAC: it is named in the literature on targeted protein degradation; ubiquitination databases record sites on it; its protein half-life has been measured; a small molecule that binds it is known.
Target class: Protein Kinase; Other protein kinase NAK family; Other protein kinase group; Enzyme; Kinase
Chemical probes: CA93.0 (high quality), DGY-06-116 (high quality), GEFITINIB
Gene: Protein-coding gene on chromosome 4 (849,275 to 932,411, reverse strand). Ensembl gene ENSG00000178950.
Subcellular location: Cytoplasm, perinuclear region; Golgi apparatus, trans-Golgi network; Cell junction, focal adhesion; Cytoplasmic vesicle, clathrin-coated vesicle
Subcellular location (Human Protein Atlas): Golgi apparatus; Vesicles
Pathways (Reactome):
Vesicle-mediated transport: Clathrin-mediated endocytosis; Golgi Associated Vesicle Biogenesis
Gene Ontology:
Molecular function: protein binding; protein serine/threonine kinase activity; clathrin binding; cyclin binding; protein folding chaperone; ATP binding; protein kinase activity; protein serine kinase activity
Biological process: clathrin coat assembly; clathrin coat disassembly; clathrin-dependent endocytosis; Golgi organization; Golgi to lysosome transport; negative regulation of neuron projection development; protein localization to Golgi apparatus; protein localization to plasma membrane; receptor-mediated endocytosis; regulation of clathrin coat assembly; endoplasmic reticulum organization; protein folding; synaptic vesicle uncoating
Cellular component: clathrin-coated vesicle; Golgi apparatus; membrane; vesicle; cytosol; focal adhesion; perinuclear region of cytoplasm; presynapse
Genetic constraint (gnomAD): Loss-of-function variants: 74 observed, 130.71 expected, observed/expected ratio (o/e) 0.57, 90% interval 0.47 to 0.69. The synonymous counts are far from expectation, so gnomAD's model fits this gene poorly and the ratio says little. Missense variants: 1,688 observed, 1,745.2 expected, observed/expected ratio (o/e) 0.97, 90% interval 0.93 to 1.01. Synonymous variants: 881 observed, 753.79 expected, observed/expected ratio (o/e) 1.17, 90% interval 1.11 to 1.24.
Homologues: Orthologues: macaque GAK (98% identical), chimpanzee GAK (90% identical), dog GAK (84% identical), mouse Gak (83% identical), rat Gak (83% identical), guinea pig GAK (82% identical), pig GAK (80% identical), rabbit GAK (74% identical), tropical clawed frog gak (68% identical), zebrafish gak (64% identical), Drosophila melanogaster aux (34% identical), Caenorhabditis elegans dnj-25 (14% identical). Paralogues in human: DNAJC6 (34% identical).
Diseases named in the same sentence as GAK in open-access papers:
GAK is named in the same sentence as 60 diseases in open-access papers, as found by Europe PMC text mining. Sharing a sentence is not in itself a finding about the gene and the disease. The quoted sentences say what the papers report.
Parkinson disease (27 papers, 2010 to 2025). A progressive degenerative disorder of the central nervous system characterized by loss of dopamine producing neurons in the substantia nigra and the presence of Lewy bodies in the substantia nigra and locus coeruleus. "We previously identified a role for dAuxilin (dAux), the fly homolog of Cyclin G-associated kinase, in glial autophagy contributing to Parkinson’s disease (PD)." (PMID 39807990, 2025). "A GWAS of Parkinson’s disease has identified the TMEM175/GAK/DGKQ region at chromosome 4p16.3 as a significant risk locus of this disease." (PMID 37238672, 2023). "Diseases associated with GAK include prostate sealing ring cell adenocarcinoma and Parkinson's disease 15, autosomal recessive early onset." (PMID 37932811, 2023). "The TMEM175/GAK/DGKQ locus was the third strongest risk locus in a GWA study of Parkinson’s disease and has been described as a potential drug target." (PMID 34745218, 2021). "Other protein kinases have also been linked to Parkinson's disease, including a cyclin G-associated kinase (GAK) encoded by the GAK gene, which was identified by GWAS." (PMID 34335440, 2021). "The association of single nucleotide polymorphisms (SNPs) in the GAK/DGKQ locus on chromosome 4 with Parkinson’s disease raised the possibility that TMEM175 gene in this region has pathophysiological significance in the neurodegenerative disorder." (PMID 34638858, 2021). "Intriguingly, GAK, which codes for the auxilin paralog GAK, is a candidate gene for a Parkinson's disease risk locus on chromosome 4." (PMID 34897416, 2021). "The susceptibility of the GAK rs1564282 variant in Parkinson’s disease (PD) in Europeans was identified using a series of published genome-wide association studies." (PMID 34868266, 2021). "These GAK inhibitors also represent tools to study GAK function in different disease areas where GAK is implicated (i.e. viral infections, cancer, and Parkinson’s disease)." (PMID 34421588, 2021). "Our previous study implicated that neuronal auxilin(aux), a clathrin-uncoating factor and homolog of Cyclin-G-associatedkinase (GAK), is a causative factor of Parkinson's disease (PD) usingDrosophila as a model." (PMID 34612709, 2021). "GAK (auxilin-2) has known involvement in synaptic function and neurological diseases, and is associated by GWAS with overlapping properties of Parkinson’s Disease and autoimmune diseases." (PMID 33115496, 2020). "GAK has been identified as a gene associated with Parkinson's disease in several genome-wide association studies screens." (PMID 30623173, 2018). "GAK is also implicated in Parkinson's disease through genome-wide association studies." (PMID 30623173, 2018). "Interestingly, genome wide association studies have linked DnaJC26 (GAK) to Parkinson’s disease susceptibility." (PMID 25071450, 2014). "Furthermore, human GAK has recently been implicated as a susceptibility gene in familial Parkinson disease, and the neurodegenerative phenotype observed in GAK morphants certainly supports this conclusion." (PMID 20082716, 2010). "GAK is also involved in regulation of hepatitis C viral entry and assembly, and pathogenesis of Parkinson's disease." (PMID 26438695, 2015). "Similarly, GAK and RAB29 are implicated in mitochondrial dysfunction, which has been linked to urinary biomarker research in Parkinson’s disease." (PMID 40130009, 2025). "Several of these have been associated with other neurodegenerative disorders (ZDHHC17 with Huntington’s disease, SYT11 and GAK with Parkinson’s disease and GABRB3 with dementia with Lewy bodies), and may be of special interest for future studies." (PMID 34202490, 2021). "GAK is the major therapeutic target of Parkinson's disease and novel chemicals that inhibit its kinase activity are currently being developed; gefitinib and luteolin may also be clinically useful for the treatment of prostate cancer and osteosarcoma." (PMID 24971999, 2014).
Parkinson disease (continued). "Remarkably, the Parkinson disease (PD)-related gene CHCHD2 is also significantly downregulated in all mutant lines, while GAK is upregulated." (PMID 30057263, 2018). "These hub genes, particularly VPS35, VPS29, and GAK, hold potential not only as molecular drivers of Parkinson’s disease but also as candidates for developing non-invasive urinary biomarkers for early diagnosis and therapeutic targeting." (PMID 40130009, 2025).
prostate carcinoma (8 papers, 2014 to 2025). A carcinoma that arises from epithelial cells of the prostate gland. "The combined effects of luteolin and gefinitib, a selective tyrosine kinase inhibitor that suppresses both EGFR and the kinase activity of cyclin G-associated kinase (GAK), on PC-3 prostate cancer cells were investigated in 2014." (PMID 40728967, 2025). "Besides the conventional EGFR inhibitors erlotinib and gefitinib, the herbal flavonoid luteolin showed effect in suppressing EGFR by down-regulating the Ser/Thr kinase activity of cyclin G-associated kinase (GAK) in prostate cancer cells." (PMID 26305257, 2015). "Although EGFR and GAK are expressed at high levels in prostate cancer and their enhanced expression is associated with poor prognosis, administration of gefitinib alone is ineffective and combined administrations of gefitinib and radiation therapy or docetaxel have limited therapeutic effects." (PMID 24971999, 2014). "Other studies have shown that GAK is a transcriptional coactivator of the androgen receptor (AR), a ligand-dependent transcription factor highly expressed in prostate cancer." (PMID 28472763, 2017). "Here, we report that GAK expression is positively correlated with the Gleason score in surgical specimens from prostate cancer patients." (PMID 24971999, 2014). "In vitro kinase assays were also used to determine the effects of luteolin (a flavonoid) and resveratrol (a polyphenol) on GAK activity; these compounds inhibit the growth of prostate cancer cell lines." (PMID 24971999, 2014). "Expression of GAK is known to increase during prostate cancer progression to androgen independence and has been positively correlated with Gleason scores in resections from prostate cancer patients." (PMID 31698822, 2019). "Indeed, GAK is modified and overexpressed in cancer cell lines and that GAK is overexpressed in surgical specimens from prostate cancer patients." (PMID 24971999, 2014). "Taken together, these findings suggest that GAK may be a new therapeutic target for prostate cancer and osteosarcoma." (PMID 24971999, 2014). "Notably, a previous study using a neo-adjuvant hormone therapy tissue microarray demonstrated that GAK expression increases significantly during the progression of prostate cancer to androgen independence." (PMID 24971999, 2014).
breast carcinoma (4 papers, 2021 to 2026). "NOD1 is significantly expressed in ALDH+ breast cancer stem cells and works in conjunction with cyclin G-associated kinase (GAK) to phosphorylate and facilitate the lysosomal degradation of NUMB." (PMID 40792257, 2025). "Notably, NOD1 exhibited elevated expression levels on aldehyde dehydrogenase breast cancer stem cells (BCSCs) and worked in conjunction with cyclin g-associated kinase (GAK) to phosphorylate NUMB, thereby promoting its lysosomal degradation." (PMID 41503829, 2026). "NOD1 was highly expressed on ALDH+ breast cancer stem cells (BCSCs) and cooperated with GAK to phosphorylate NUMB and promote its lysosomal degradation, thereby activating the NOTCH1-HEY1 signaling pathway to increase BCSCs." (PMID 38437016, 2024). "We therefore explored whether GAK regulated NUMB by phosphorylation in NOD1-overexpressing breast cancer cells." (PMID 38437016, 2024). "To determine whether ETBF or BFT-1 influenced the interaction between NOD1 and GAK, we transiently transfected breast cancer cells with FLAG-tagged NOD1 or GAK." (PMID 38437016, 2024). "GAK-knockdown in NOD1-overexpressing breast cancer cells significantly inhibited NOD1-induced cell proliferation, suppressed BCSC enrichment and re-sensitized cells to DTX, suggesting that GAK-knockdown reversed phenotype induced by NOD1-overexpressing." (PMID 38437016, 2024).
viral infection (4 papers, 2012 to 2024). "In addition to anti-inflammatory properties, baricitinib is a JAK inhibitor with potential antiviral effects, inhibiting AP2-associated kinase 1 (AAK1) and cyclin G-associated kinase (GAK) involved in SARS-CoV-2 endocytosis, i.e. viral infection of host cells." (PMID 35707401, 2022). "Conservative requirement for AAK1 and GAK across viral families may suggest that the identified inhibitors could potentially be used for treating HCV-HIV co-infection and possibly a broader spectrum of viral infections." (PMID 22916011, 2012). "Furthermore, AAK1 and GAK have not been reported to mediate a viral infection to date." (PMID 22916011, 2012).
COVID-19 (3 papers, 2021 to 2023). A disease caused by infection with severe acute respiratory syndrome coronavirus 2. "Interestingly, 008 and 039 showed robust activity in degrading GAK and AAK1 simultaneously, indicating the possible use in antiviral treatment for coronavirus disease 2019." (PMID 37196766, 2023). "Currently, optimizing valuable hits (3,5-disubstituted pyrrolo [2,3-b] pyridines) or use of exciting medication as potent GAK and AAK1 inhibitors could be a promising approach to manage COVID-19 INFECTION." (PMID 34222852, 2021). "GAK and AAK1 inhibitor such as baricitinib have been wished for as a potential therapeutic agent for COVID-19 treatment by decreasing the viral entry, though no investigational work has been conducted to verify its mechanism of action." (PMID 34222852, 2021).
melanoma (3 papers, 2019 to 2021). A malignant, usually aggressive tumor composed of atypical, neoplastic melanocytes. "The expression levels of ZCCHC10 proteins were significantly reduced in all six melanoma cell lines (A2058, SKMEKL28, G361, HMV1, CRL1597 and GAK) when compared to normal human epidermal melanocyte cells." (PMID 31404068, 2019).
osteosarcoma (3 papers, 2014 to 2021). A usually aggressive malignant bone-forming mesenchymal neoplasm, predominantly affecting adolescents and young adults. "Osteosarcoma cells of patients with a poor prognosis display increased expression of GAK in the nucleus, and siRNA-mediated knockdown of GAK decreases the propagation of osteosarcoma cells." (PMID 29559659, 2018). "GAK is overexpressed in U2OS osteosarcoma cells, which lack EGFR expression, and knockdown of GAK inhibits their proliferation." (PMID 24971999, 2014). "GAK appears to be essential for cell death because co-administration of gefitinib and luteolin to EGFR-deficient U2OS osteosarcoma cells also had a greater effect on cell viability than administration of either compound alone." (PMID 24971999, 2014). "It has been proved that osteosarcoma cell proliferation and survival are dependent on GAK." (PMID 34041269, 2021). "Unlike other osteosarcoma cell lines (HOS, MG-63, and KHOS/NP), U2OS cells lack expression of the EGFR, the well-known target of gefitinib; therefore, GAK is a putative bona fide target of gefitinib in these cells." (PMID 24971999, 2014).
Parkinsonism (3 papers, 2016 to 2024). Characteristic neurologic anomaly resulting from degeneration of dopamine-generating cells in the substantia nigra, a region of the midbrain, characterized clinically by shaking, rigidity, slowness of movement and difficulty with walking and gait. "Several other vacuolar protein sorting receptors, such as VPS35, DNAJC26 (GAK) and DNAJC13 (RME-8) are also implicated in monogenic parkinsonism or PD risk." (PMID 38559229, 2024).
cervical carcinoma (2 papers, 2008 to 2024). A carcinoma arising from either the exocervical squamous epithelium or the endocervical glandular epithelium. "Recent research suggests that FBXO22 may facilitate the ubiquitin-mediated degradation of cyclin G-associated kinase (GAK), thereby inhibiting the proliferation and metastasis of cervical cancer cells." (PMID 39048965, 2024).
cholangiocarcinoma (2 papers, 2015 to 2017). A carcinoma that arises from the intrahepatic biliary tree (intrahepatic cholangiocarcinoma) or from the junction, or adjacent to the junction, of the right and left hepatic ducts (hilar cholangiocarcinoma). "A multitude of cancers would be good clinical candidates for specific GAK inhibitors including cholangiocarcinoma, as epithelial bile duct cancers are one of the highest mutated FBXW7 tumours, have poor prognosis and a paucity of therapeutic agents." (PMID 28829765, 2017).
chordoma (2 papers, 2022 to 2023). Chordomas are rare malignant tumors arising from embryonic remnants of the notochord in axial skeleton. "While exploring cyclin G associated kinase (GAK) as a potential collateral target to treat chordoma, we identified a series of potent EGFR inhibitor starting points based on the 4-anilinoquinazoline scaffold, exemplified by 110,12." (PMID 35896603, 2022). "EGFR inhibitors, identified as a potential therapeutic target for chordoma by screening 1097 focused libraries of compounds, and specific inhibitors that target EGFR and cyclin G-associated kinase (GAK) showed efficacy in chordoma cells." (PMID 37111759, 2023).
dengue (2 papers, 2021 to 2024). "Cyclin G-associated kinases (GAK) phosphorylated adaptor protein complexes (APs), thereby regulating membrane transport and promoting the dengue virus infection." (PMID 34347790, 2021).
gastric cancer (2 papers, 2015 to 2019). A primary or metastatic malignant neoplasm involving the stomach. "Gene expression of GAK (cyclin G-associated kinase) was also found to be negatively correlated in stomach cancer, and patients with a GAKlow phenotype had poorer overall survival." (PMID 30578123, 2019). "While GAK has been shown to promote oncogenesis in some cancers, in stomach cancer it appears that higher expression of GAK may be beneficial." (PMID 30578123, 2019).
glomerulosclerosis (2 papers, 2020 to 2025). A hardening of the kidney glomerulus caused by scarring of the blood vessels. "To examine the role of GAK, a protein that functions to uncoat clathrin during endocytosis, we generated podocyte-specific Gak-knockout mice (Gak-KO), which developed progressive proteinuria and kidney failure with global glomerulosclerosis." (PMID 33208557, 2020).
adenoma (1 paper, 2005). A neoplasm arising from the epithelium. "On the other hand, GAK was the most downregulated gene in the early invasive carcinoma group relative to the adenoma group." (PMID 15785755, 2005).
astrocytoma (1 paper, 2018). "Since auxilin and GAK are required for efficient clathrin rearrangement and since auxilin expression is high in neuronal cells, a prediction of these results is that auxilin and/or GAK should also be required for P2Y12 uptake in 1321N1 astrocytoma cells." (PMID 30228161, 2018). "However, GAK does not appear to be capable of compensating for loss of auxilin in the astrocytoma cells." (PMID 30228161, 2018).
bone cancer (1 paper, 2026). A primary or metastatic malignant neoplasm affecting the bone or articular cartilage. "Together with previous studies that demonstrated GAK as a promising target to bone cancer, this brings the perspective to further investigate in this direction." (PMID 41518355, 2026).
chronic kidney disease (1 paper, 2020). Impairment of the renal function secondary to chronic kidney damage persisting for three or more months. "Evidence for reduced expression of cyclin G associated kinase (GAK) in glomeruli of patients with chronic kidney disease was observed in the Nephroseq human database, and GAK was found to be associated with the decline in kidney function." (PMID 33208557, 2020). "Reduced cyclin G associated kinase (GAK) expression associates with diabetic and chronic kidney diseases, and GAK ablation in mice causes kidney failure due to calpain activation." (PMID 33208557, 2020).
colon cancer (1 paper, 2017). "Furthermore, the entire colon cancer cell panel was relatively insensitive to GAK inhibition despite good protein knockdown." (PMID 28829765, 2017).
colorectal adenoma (1 paper, 2005). An adenoma that arises from the colon or rectum. "Thus, our results suggest that downregulation of GAK plays an important role in the progression from colorectal adenoma to carcinoma." (PMID 15785755, 2005).